PCAT1 (prostate cancer associated transcript 1)
Synonyms: PCAT-1; PCA1; PiHL; LOC105375751
Gene: Long non-coding RNA gene on chromosome 8 (126,556,323 to 127,419,050, forward strand). Ensembl gene ENSG00000253438.
Diseases named in the same sentence as PCAT1 in open-access papers:
PCAT1 is named in the same sentence as 58 diseases in open-access papers, as found by Europe PMC text mining. Sharing a sentence is not in itself a finding about the gene and the disease. The quoted sentences say what the papers report.
prostate carcinoma (89 papers, 2012 to 2025). A carcinoma that arises from epithelial cells of the prostate gland. "Studies have shown that prostate cancer-associated transcript 1 (PCAT-1) functions as an oncogenic factor initially described in prostate cancer patients." (PMID 40468332, 2025). "In prostate cancer, genome-wide RNA-Seq analysis identified many lncRNAs that are up- or down-regulated in prostate cancer, such as PCA3, PCGEM1, and PCAT-1 are highly associated with prostate cancer." (PMID 39403375, 2024). "The prostate cancer associated transcript 1 (PCAT1) was initially demonstrated to exert oncogenic roles in prostate cancer." (PMID 39640681, 2024). "PCAT1 (Prostate cancer-associated transcript-1), located at chromosome 8q24 is a lncRNA that was originally identified in prostate cancer." (PMID 39044190, 2024). "A notable illustration is PCAT-1 dysregulation, which is strongly linked to the development of prostate cancer." (PMID 36949898, 2023). "Another locus “chr8:127102614”, which was in intron of non-coding gene PCAT1, showed highest variance of allele lengths in African samples, and this site was in high LD with multiple GWAS SNPs associated with prostate carcinoma." (PMID 37045857, 2023). "MiR-3667-3p targets the lncRNA (long non-coding RNA) PCAT-1 (Prostate cancer associated transcript-1) in prostate cancer." (PMID 37719019, 2023). "For instance, the lncRNA prostate cancer-associated transcript 1 (PCAT-1) is upregulated in prostate cancer and associated with poor prognosis and tumor progression." (PMID 37232821, 2023). "selected lncRNA PCAT1 which is related to the risk of prostate cancer to reveal the underlying mechanism." (PMID 35592755, 2022). "Prostate cancer-associated transcript 1(PCAT1) was initially identified as an overexpressed lncRNA in prostate cancer tissues, which has also been proved to be abnormally expressed in various malignant tumors and to play a carcinogenic role." (PMID 35573683, 2022). "Over-expression of the lncRNA prostate cancer-associated Transcript-1 (PCAT-1) promotes prostate cancer cell proliferation through MYC and is closely associated with poor prognosis in CRC patients." (PMID 36362222, 2022). "“Prostate Cancer Associate Transcript 1” (PCAT-1) is a prostate cancer-specific lincRNA involved in DSB repair." (PMID 34203749, 2021). "The SNP is associated with decreased levels of PCAT1-short and increased levels of PCAT1-long, with the long isoform associated with prostate cancer progression." (PMID 33499210, 2021). "The expression of another prostate related lncRNA, PCAT1 (Prostate Cancer Associated Transcript 1), is also modulated at the transcriptional level by a cancer-associated SNP with pivotal function in prostate cancer." (PMID 34449663, 2021). "For example, in PTEN-deficient prostate cancer, lncRNA PCAT1 directly binds to FKBP51 and replaces PHLPP in the PHLPP/FKBP51/IKKα complex, thereby activating AKT and NF-κB signals and accelerating the progression of the disease." (PMID 33584827, 2021). "Initially, PCAT1 was reported to be implicated in early prostate cancer cell proliferation, yet recently it was shown to be involved also in castration-resistant, advanced prostate tumors." (PMID 34449663, 2021). "For example, SAL-RNAs was classified as Senescence-associated lncRNAs, and PCA3/PCAT1 as Prostate cancer-associated transcripts (PCATs)." (PMID 33240586, 2020). "Here we show that the 8q24 prostate cancer rare variant, rs72725854 is present in an enhancer and regulates multiple lncRNAs genes namely, PCAT1, PRNCR1, PVT1, and proto-oncogene MYC in the region." (PMID 32680982, 2020). "In another example, prostate cancer risk variants at 8q24 increase the activity of an enhancer for the PCAT1 lncRNA." (PMID 31910864, 2020). "In previous studies on prostate cancer cells, PCAT-1 expression was found to cause functional impairment in homologous recombination with an inhibitory effect on BRCA2 tumor suppressor." (PMID 31319040, 2020).
prostate carcinoma (continued). "PCAT-1, identified as prostate cancer–associated ncRNA transcripts 1, was also demonstrated to be associated with worse prognosis clinical outcomes in CRC." (PMID 33203797, 2020). "While the PCAT1 rs1902432 SNP was also reported to be significantly associated with the risk of prostate cancer in Chinese population." (PMID 31253700, 2019). "One potential diagnosis marker is the prostate cancer-associated transcript 1 (PCAT-1), which can be identified in the urine of prostate cancer patients." (PMID 30781588, 2019). "Prostate cancer-associated transcript 1 (PCAT1) is a newly discovered lncRNA located in 8q24.21, which is first demonstrated to promote deterioration and progression of prostate cancer." (PMID 31464517, 2019). "This study will explore the expression and effects of prostate cancer-associated ncRNA transcript 1 (PCAT-1) in MM." (PMID 31777580, 2019). "Only the PCAT1 rs1902432 SNP was reported to be significantly associated with other cancer, namely, increasing the risk of prostate cancer." (PMID 31253700, 2019). "Concerning PCAT1 SNPs, only one investigation has reported their association with cancer susceptibility, which found that PCAT1 rs1902432 tagSNP was associated with prostate cancer risk." (PMID 31253700, 2019). "Long non-coding RNA prostate cancer associated transcript-1 ncRNA (lncRNA-PCAT-1) plays an important role in the progression of prostate cancer." (PMID 31338011, 2019). "The same research group used a transcriptome sequencing across a prostate cancer cohort to identify PCAT-1 as an unannotated lincRNA implicated in disease progression." (PMID 29671405, 2018). "Prostate cancer-associated intergenic non-coding RNA transcript 1 (PCAT1), has also been extensively investigated and found to be critical for prostate cancer pathogenesis." (PMID 28272371, 2017). "Prostate Cancer Associated Transcript 1 (PCAT-1) was originally identified as a biomarker of prostate cancer, but subsequently it was also found to be involved in the progression of colorectal cancer." (PMID 29165379, 2017). "LncRNA PCAT-1 (prostate cancer-associated ncRNA transcripts 1) is involved with human prostate cancer progression." (PMID 27888635, 2017). "Recently, a novel lncRNA, prostate cancer associated-transcript 1 (PCAT1), was identified to be highly overexpressed in aggressive prostate cancer." (PMID 25663854, 2015). "Several nlincRNAs from a prostate cancer associated chromosomal locus, 8q24, are up-regulated in cancer along with other known prostate cancer associated genes including PCAT-1, PVT1, and PCAT-92." (PMID 25933431, 2015). "PCAT-1 (prostate cancer-associated intergenic non-coding RNA transcript 1) is transcribed from chromosome 8q24, a locus that is associated with prostate cancer risk and susceptibility." (PMID 26110379, 2015). "High-throughput sequencing showed that prostate cancer–associated ncRNA transcript 1 (PCAT-1) is a prostate-specific regulator of cell proliferation in PCa and a target of PRC2." (PMID 23936419, 2013). "Transcriptome sequencing of a prostate cancer cohort has identified an unannotated ncRNA PCAT-1 as a transcriptional repressor linked to PCa progression." (PMID 23957008, 2013). "Another long ncRNA PCAT-1 (prostate cancer-associated transcript 1), which is over-expressed in a subset of prostate cancers, particularly metastatic tumors, is known to regulate cell proliferation in prostate cancer progression." (PMID 23087702, 2012). "PCAT1 is another long non‐coding RNA associated with prostate cancer risk." (PMID 39099406, 2024). "PCAT1 interacts with the androgen receptor and lysine-specific demethylase to promote prostate cell growth providing a mechanism by which genetic variants increase risk of prostate cancer." (PMID 31910864, 2020). "Prostate cancer-associated transcript 1 (PCAT-1) was initially identified in prostate cancer." (PMID 30987615, 2019).
prostate carcinoma (continued). "The molecular mechanisms underlying the altered expression of PCAT-1 in CRC remain unclear although it has been reported to be regulated by the PRC2 complex in prostate cancer cells." (PMID 26637808, 2016). "PCAT-1 was discovered in 2011 by RNA-sequencing and is implicated in prostate cancer progression." (PMID 27148353, 2016). "In addition, dysregulated lncRNAs in drug-resistant and -sensitive PCa cells were identified by RNA sequencing, and we identified that prostate cancer-associated transcript 1 (PCAT1) was highly expressed in the docetaxel-resistant PCa cell lines and clinical samples." (PMID 35402284, 2022). "PCAT1 was upregulated in docetaxel (DTX)-resistant PCa prostate cancer cells and in prostate cancer (PCa) patients, whereas PCa patients with higher serum PCAT1 levels had an unsatisfactory response to DTX chemotherapy." (PMID 38539832, 2024). "Conversely, prostate cancer cells with PCAT1 knockdown developed tolerance toward ferroptosis induced by erastin or DTX treatments, reducing the lipid ROS content and iron overload." (PMID 38539832, 2024). "PCAT-1 promotes prostate cancer cell proliferation through positive post-transcriptional regulation of c-Myc." (PMID 37719019, 2023). "The lncRNA PCAT1 in prostate cancer upregulates androgen-responsive gene levels through the recruitment of androgen receptor and lysine-specific demethylase 1, leading to the growth and proliferation of prostate cancer cells." (PMID 36936418, 2023). "Transcription factor AP-2 gamma (TFAP2C)-dependent PCAT1 suppresses ferroptosis of prostate cancer cells." (PMID 36230902, 2022). "Transcription factor AP-2 gamma (TFAP2C) transcriptionally activates lncRNA PCAT1 to suppress ferroptosis of prostate cancer cells by interacting with c-Myc." (PMID 36230902, 2022). "lncRNA PCAT1 has been reported to be able to promote the proliferation of prostate cancer cells by binding to the cMyc protein." (PMID 36093435, 2022). "Prostate cancer-related transcript 1 (PCAT1) was originally identified as an over-expressed lncRNA in prostate cancer by RNA sequencing, which can promote the progression of prostate cancer." (PMID 35241975, 2022). "PCAT1 promotes prostate cancer proliferation through c-MYC via sponging miR-3667-3p and FSCN1 via sponging miR-145-5p." (PMID 35075375, 2022). "PCAT1 stimulates prostate cancer progression by activating AKT and nuclear factor (NF)-κB signaling." (PMID 35075115, 2022). "PCAT-1 is upregulated in prostate cancer and promotes the proliferation of prostate cancer cells through PRC2 and cMyc proteins." (PMID 35103065, 2022). "Among Chr8q24 gene located approximately 725 kb upstream of the MYC oncogene, PCAT1 was initially found in prostate cancer and is involved in the occurrence and development of prostate cancer." (PMID 35692795, 2022). "In castration-resistant prostate cancer samples, duplications hotspots were evident in the region hosting PCAT1 and PRNCR1." (PMID 33499210, 2021). "For example, Cluster77 contains four lincRNAs, PCAT1 involved in prostate cancer development, PCAT2 associated with prostate cancer, PRNCR1 associated with include prostate disease and prostate cancer." (PMID 34906173, 2021). "Another prostate cancer-associated variant at lncRNA PCAT1 rs7463708 increases binding of transcription factor ONECUT2 to the PCAT1 promoter, resulting in upregulation of PCAT1 and prostate transformation." (PMID 34336850, 2021). "For example, prostate cancer-related transcription (PCAT) PCAT1 has been proved to play a significant role in the biological function of prostate cancer." (PMID 33791072, 2021). "PCAT1 was identified as an lncRNA overexpressed in a subset of prostate cancer patients, where it promotes cell proliferation." (PMID 33329688, 2020). "LncRNA PCAT-1 contributes to prostate cancer tumorigenesis through modulating FSCN1 and sponging miR-145-5p." (PMID 32781986, 2020).
prostate carcinoma (continued). "Previously, PCAT-1 was characterized as a practical non-coding RNA particle, which was involved in progression of the subjects with prostate cancer." (PMID 31338011, 2019). "Study findings support future efforts in clinical development of PCAT1 as a therapeutic target and also a potential biomarker for castration-resistance prostate cancer." (PMID 30773595, 2019). "Modulation of AKT1 gene was noted in the transcriptomic data of PCAT-1 depleted prostate cancer cells." (PMID 30987615, 2019). "None of these previous studies, however, investigated the role of PCAT1 in a setting relevant to castration therapy that is the mainstay of prostate cancer treatment." (PMID 30773595, 2019). "Several SNVs are implicated in the expression of cancer-associated lncRNAs—including CCAT2 in colorectal cancers and PCAT-1 in prostate cancer." (PMID 30934003, 2019). "ONECUT2 modulates the expression of oncogenic lncRNA PCAT1 in prostate cancer, indicating its potential role in prostate cancer development." (PMID 30655535, 2019). "PCAT1, a long non-coding RNA (lncRNA), was first described in 2011 as a prostate-specific regulator of cell proliferation in prostate cancer." (PMID 30773595, 2019). "PCAT-1 levels are inversely correlated with RAD51 foci formation when prostate cancer cells are treated with the PARP1 inhibitors olaparib or ABT-888." (PMID 30373256, 2018). "Based upon our proposed method, prostate cancer was predicted to be associated with H19, MALAT1, CDKN2B-AS1, HOTAIR, PCAT1, SRA1, XIST." (PMID 29671405, 2018). "PCAT-1 is the first lincRNA identified that participates in DSB repair in prostate cancer, and extends the “BRCA-ness” paradigm to include lncRNAs, in addition to mutations in DNA repair genes." (PMID 30373256, 2018). "Previously, it has been demonstrated that PCAT-1 expression in prostate cancer cells leads to a functional insufficiency in homologous recombination through its inhibitory effect on the BRCA2 tumor suppressor." (PMID 28989584, 2017). "It has been shown that PCAT-1 is up-regulated in prostate tumor tissues and promotes prostate cancer cell proliferation via PRC2." (PMID 26637808, 2016). "The lncRNA prostate cancer-associated ncRNA transcript 1 (PCAT-1) is located in the chromosome 8q24 gene desert approximately 725 kb upstream of the c-MYC oncogene, and is involved in the progression of human prostate cancer." (PMID 26637808, 2016). "PCAT-1 is up-regulated in prostate cancer tumor tissues and it has been shown to promote cell proliferation through association with polycomb repressive complex 2 (PCR2) as a transcriptional repressor." (PMID 27148353, 2016). "Knock down of PCAT1 in androgen dependent prostate cancer cell line resulted in alteration of hundreds of genes." (PMID 26082843, 2015). "PCAT-1 is particularly up-regulated in a subset of high-grade localized and metastatic prostate cancers." (PMID 26110379, 2015). "These authors found that the prostate cancer outlier lncRNA PCAT-1 can regulate the cellular response to genotoxins by repressing the expression of BRCA2 to create a deficiency in homologous recombination (HR)." (PMID 26110379, 2015). "After knocking down PCAT-1 in prostate cancer cells, gene expression profiling identified 255 up-regulated genes and 115 down-regulated genes." (PMID 26110379, 2015). "In this work, the increased levels of lincRNA PCAT-1 were characterized as conferring poor prognosis to prostate cancer patients." (PMID 23875687, 2013). "PCAT-1 is transcribed from chr8q24 and promotes prostate cancer cell proliferation by regulating target genes in trans, including BRCA2 (breast cancer early-onset 2), CENPF (centromere protein F) and CENPE (centromere protein E)." (PMID 23875687, 2013). "In prostate cancer, researchers found that lncRNA SNHG3, lncRNA prostate cancer-associated transcript 1 (PCAT1) and lncRNA OIP5-AS1 could affect SLC7A11 mRNA expression through different regulatory mechanisms." (PMID 37127605, 2023).